TAGLN2 (transgelin 2)
Diseases named in the same sentence as TAGLN2 in open-access papers (continued):
Sharing a sentence is not in itself a finding about the gene and the disease.
bacterial sepsis (1 paper, 2017). "In this respect, development of cell-permeable peptides that exhibit TAGLN2 functions may have potential clinical value for the treatment of bacterial sepsis." (PMID 28821818, 2017). "Thus, our findings suggest that TAGLN2 is an essential factor of macrophages for host defense, maintaining protective immunity in bacterial sepsis." (PMID 28821818, 2017).
cervical squamous cell carcinoma (1 paper, 2022). A squamous cell carcinoma arising from the cervical epithelium. "In addition, the inhibition of TAGLN2 in human cervical squamous cell carcinoma (SCC) and uterine SCC cells has been shown to significantly inhibit tumor growth and invasion." (PMID 35281112, 2022).
cognitive decline (1 paper, 2021). "Finally, combinations of four molecules improved prediction of both AD (protein 14-3-3 zeta/delta, clusterin, interleukin-15, and transgelin-2) and cognitive decline (protein 14-3-3 zeta/delta, clusterin, cholesteryl ester 27:1 16:0 and monocyte chemoattractant protein-1)." (PMID 33794997, 2021).
diabetes (1 paper, 2017). "In this study, we focused on transgelin-2 to decipher the underlying mechanisms that mediate its upregulation in diabetes-associated PDAC." (PMID 28521289, 2017). "Our data support a novel mechanism in diabetes-associated PDAC by which transgelin-2 mediates proliferation of PDAC cells upon insulin stimulation." (PMID 28521289, 2017). "Further studies are also required to analyze the biological function of transgelin-2 in diabetes-associated PDAC." (PMID 28521289, 2017). "We presume that transgelin-2 and its homolog are extensively involved in promoting diabetes-associated PDAC." (PMID 28521289, 2017). "The insulin/SREBP-1/transgelin-2 network should be further explored as a diagnostic marker or a novel therapeutic target for diabetes-associated PDAC." (PMID 28521289, 2017). "The axis of insulin/SREBP-1/transgelin-2 links the association between diabetes and PDAC, suggesting that this signaling pathway represents new therapeutic targets and molecular markers for this subgroup of PDAC." (PMID 28521289, 2017). "Here, we found that transgelin-2 is dominantly expressed in PDAC patients with diabetes, which suggests that transgelin-2 is involved in progression of diabetes-associated PDAC." (PMID 28521289, 2017). "Among these factors, histological grade (odds ratio [OR] =5.293, p=0.030), tumor size (OR=5.357, p=0.017) and diabetes (OR=4.623, p=0.020) were proven to be independent predictors of high transgelin-2 expression by multivariate logistic regression analysis." (PMID 28521289, 2017). "In diabetes-associated PDAC, hyperinsulinemia promotes the maturation and transcriptional activity of SREBP-1, which leads to an increase of transgelin-2." (PMID 28521289, 2017). "Transgelin-2 was predominantly overexpressed in a subgroup of PDAC patients with diabetes." (PMID 28521289, 2017). "The expression pattern of transgelin-2 is unable to distinguish between diabetes and PDAC." (PMID 28521289, 2017). "Thus, blocking transgelin-2 expression is a potential therapeutic strategy to treat PDAC occurring concomitantly with diabetes." (PMID 28521289, 2017). "We investigated whether transgelin-2 and SREBP-1 were correlated in diabetes-associated PDAC." (PMID 28521289, 2017). "Thus, PDAC tissues from patients with diabetes display a high level of transgelin-2." (PMID 28521289, 2017). "PDAC tissues showed high expression of transgelin-2 and SREBP-1, which were mainly distributed in patients with diabetes." (PMID 28521289, 2017). "PDAC patients with diabetes showed high expression of transgelin-2 compared with those without diabetes." (PMID 28521289, 2017). "A homolog of transgelin-2, transgelin, is also highly expressed in PDAC patients with diabetes." (PMID 28521289, 2017). "The χ2 test demonstrated that the levels of transgelin-2 and SREBP-1 were correlated in PDAC patients with diabetes compared to those without diabetes." (PMID 28521289, 2017).
E. coli (1 paper, 2020). "The involvement of cathepsin S, transgelin 2 and C-X-C motif chemokine 13 with other infections provides a foundation for the evaluation of the potential role of these proteins in E. coli UTI pathophysiology while other proteins have been linked to viral infections." (PMID 32628701, 2020).
endometrial cancer (1 paper, 2025). Primary or metastatic malignant neoplasm involving the endometrium (mucous membrane that lines the endometrial cavity). "Depleting TAGLN2 inhibits migration and invasion in endometrial cancer, and recombinant TAGLN2-based therapies reduce tumor growth in vivo, suggesting therapeutic potential." (PMID 41373732, 2025).
high blood pressure (1 paper, 2022). "By injecting pregnant mice with Ad-TAGLN2, we successfully generated a human PE-like syndrome that resulted in high blood pressure and some adverse pregnancy outcomes." (PMID 35281112, 2022).
invasive ductal breast carcinoma (1 paper, 2013). The most common type of invasive breast carcinoma, accounting for approximately 70% of breast carcinomas. "Transgelin 2 was amongst a number of proteins found by LC-MS analysis to be overexpressed in microvessels isolated from invasive ductal breast carcinoma compared to those from adjacent non-malignant tissue." (PMID 23460839, 2013).
large bowel neoplasm (1 paper, 2013). "The oncogene Ras inhibits the expression of transgelin 2 genes in thoracic wall and large bowel neoplasm and some other cancers." (PMID 24455688, 2013).
leiomyosarcoma (1 paper, 2015). An uncommon, aggressive malignant smooth muscle neoplasm, usually occurring in post-menopausal women. "Transgelin-1 and transgelin-2 were abundant and corroborated the identity of the tumor as a leiomyosarcoma." (PMID 25861239, 2015).
lupus nephritis (1 paper, 2017). Glomerulonephritis in the context of systemic lupus erythematosus. "In lupus nephritis (n = 7), 12 ± 3% (the mean ± SEM) of CD20+B-cells (214 ± 134 cells) in the interstitium showed TAGLN2 expression." (PMID 28910360, 2017). "The control kidneys (n = 5) showed minimal inflammation and a few B-cells (1 ± 0.63 cells) were observed, which were negative for TAGLN2 (both for numbers of B-cells and TAGLN2+ B-cells, lupus nephritis versus control, p<0.05)." (PMID 28910360, 2017).
Lymphadenopathy (1 paper, 2017). Enlargement (swelling) of a lymph node. "TAGLN2+B-cells in SLE lymphadenopathy were distributed in follicular areas as well as widely outside of the follicular areas, suggesting that TAGLN2+B-cells included GC B-cells and post-GC B-cells including memory B-cells." (PMID 28910360, 2017). "CCR6 has been shown to be important for antigen-driven B-cell differentiation, which is seen in GC B-cells and memory B-cells, and the colocalization of TAGLN2 and CCR6 from the area of the GC to the perifollicular area was observed in SLE lymphadenopathy." (PMID 28910360, 2017).
malignant glioma (1 paper, 2017). A grade III or grade IV glioma arising from the central nervous system. "Both demonstrated efficient silencing of TAGLN2 in two malignant glioma cell lines with high invasive potential, U87MG and U251." (PMID 29110682, 2017). "Here, the clinical significance and potential function of TAGLN2 in malignant gliomas were investigated." (PMID 29110682, 2017).
meningioma (1 paper, 2022). A generally slow growing tumor attached to the dura mater. "Additionally, TAGLN2 is able to participate in the malignant processes of meningioma through regulating PI3K/Akt signaling pathway." (PMID 35505656, 2022).
Myocardial fibrosis (1 paper, 2024). "miR-133b binds to the 3′-UTR of PTBP1 and TAGLN2 mRNAs to regulate downstream targets, suggesting that its protective effect on cardiomyocyte apoptosis and myocardial fibrosis may occur through inhibiting PTBP1 and TAGLN2 expression." (PMID 39595980, 2024).
non-small cell lung carcinoma (1 paper, 2021). A group of at least three distinct histological types of lung cancer, including non-small cell squamous cell carcinoma, adenocarcinoma, and large cell carcinoma. "In non-small-cell lung cancer, hypoxia-inducible TAGLN2 can promote EMT by activating the IGF1RB/PI3K/AKT pathway, thereby stabilizing Snail1, which functions as an E-cadherin suppressor." (PMID 34530821, 2021).
plasma cell leukemia (1 paper, 2021). An aggressive plasma cell neoplasm characterized by the presence of neoplastic plasma cells in the peripheral blood. "Previous studies focused on transgelin-2 oncogenic potential and associations with MM transformation to plasma cell leukemia (PCL) that emphasize transgelin-2 role as a poor survival marker." (PMID 35011306, 2021).
prostate adenocarcinoma (1 paper, 2023). "Moreover, “deep deletion” of TAGLN2 was observed in prostate adenocarcinoma cases (0.81%) and all kidney renal papillary cell carcinoma cases (0.35%)." (PMID 37476180, 2023).
renal carcinoma (1 paper, 2014). A carcinoma arising from the epithelium of the renal parenchyma or the renal pelvis. "Transgelin 2 (TAGLN2), an inhibitior of cell proliferation in renal carcinoma (RCC), is an intriguing target of miR-133a." (PMID 24885635, 2014).
rheumatoid arthritis (1 paper, 2016). A chronic, systemic autoimmune disorder characterized by inflammation in the synovial membranes and articular surfaces. "Thus, transgelin-2 could be a potential therapeutic target for certain immune disorders including inflammation, hypersensitivity, rheumatoid arthritis, and experimental allergic encephalomyelitis." (PMID 27232882, 2016).
Sepsis (1 paper, 2017). Sepsis is defined as life-threatening organ dysfunction caused by a dysregulated host response to infection. "Therefore, we examined the effects of TAGLN2 knockout on cytokine production during Salmonella-induced sepsis." (PMID 28821818, 2017).
Stroke (1 paper, 2024). Sudden impairment of blood flow to a part of the brain due to occlusion or rupture of an artery to the brain. "In the CCS3 subgroup, 3 individual proteins, CA3, ITGAM (integrin subunit αM), and TAGLN2 (AUC=0.72, 0.72, and 0.7183, respectively), were predictive of recurrent stroke." (PMID 38420847, 2024).
tongue cancer (1 paper, 2021). A malignant neoplasm affecting the tongue. "Regarding transgelin-2, Ma and colleagues have revealed that the gene encoding for this protein belonged to a group of fifteen genes involved in curcumin’s therapeutic effect against human tongue cancer." (PMID 34445271, 2021).
tumor (76 papers, 2005 to 2026). "A subcutaneous mouse model was established to confirm the effects of TAGLN2 and associated axis on tumor growth in vivo." (PMID 39168971, 2024). "Knowledge about the precise biological role and underlying mechanism of Tagln2 in tumor progression is relatively limited compared to knowledge about other Tagln isoforms." (PMID 34150622, 2021). "Knowledge about the precise biological role and underlying mechanism of Tagln2 in tumor progression is relatively limited, especially in angiogenesis focused on tumor derived endothelial cells (ECs) has rarely been reported." (PMID 34150622, 2021). "Studies suggest that high levels of TAGLN2 in NSCLC cells were significantly associated with tumor development, neural invasion, and metastasis." (PMID 32457792, 2020). "TAGLN and TAGLN2 primarily participate in processes associated with a remodeling of actin cytoskeleton and their role in differentiation has been mainly described in tumor cells." (PMID 31355153, 2019). "Multivariate analysis showed that tumor size (p = 0.009) was still significantly associated with S145 phosphorylation of transgelin-2." (PMID 30041673, 2018). "Since TAGLN2 was shown to be associated with poor prognosis and tumor progression, we evaluated the role of TAGLN2 in cell proliferation in vitro." (PMID 30647847, 2018). "However, the precise biological role and underlying mechanism of TAGLN2 in tumor therapy resistance is unclear." (PMID 39168971, 2024). "Following that, promoter hypermethylation in TAGLN2 was strongly associated with tumor prognosis." (PMID 37476180, 2023). "Overall, anti-tumor drugs were overtly associated with TAGLN2 dysregulation among diverse cancers." (PMID 37476180, 2023). "Based on the positive correlation between TAGLN2 and tumor-associated macrophages, we can speculate that the tumor-promoting effect of TAGLN2 is partially due to the immunosuppressive phenotype of tumor-associated macrophages." (PMID 37476180, 2023). "In short, these results suggested that TAGLN2 may be implicated in its tumorigenic role in most tumor types by regulating the infiltration levels of immune cells such as macrophages and B cells." (PMID 37476180, 2023). "The upregulation of transgelin-2 has been associated with tumorigenesis and cancer development and may vary along with clinical stage and tumor size." (PMID 35011306, 2021). "In our previous report, we found that Tagln2 was significantly overexpressed in ECs from lung cancer tumor tissues and that its high expression was associated with advanced clinical stage, increased tumor size, and histological neural invasion." (PMID 34150622, 2021). "Surprisingly, exogenous introduction of a cell-permeable and ubiquitination site-mutated (K78R) recombinant transgelin-2 (dU-TG2P) into BMDCs significantly potentiated tumor regression in vivo, suggesting a potential use for transgelin-2 peptides in DC-mediated anticancer therapy." (PMID 33731208, 2021). "Transgelin-2 overexpression has also been linked with poor prognosis, and transgelin-2 has been proposed as a potential treatment target due to its restriction to tumor cells (to the contrary to transgelin type-1)." (PMID 35011306, 2021). "S145 phosphorylation of transgelin-2 was significantly associated with tumor stage (p = 0.027), tumor size (p = 0.02) and lymph node metastasis (p = 0.04), suggesting that transgelin-2 phosphorylation may be involved in the progression of PDAC." (PMID 30041673, 2018). "The inhibition effect on tumor cell proliferation of calycosin might be caused by upregulated transgelin 2 protein expression." (PMID 24455688, 2013). "Thus, to some extent, shifting the tumor microenvironment from immunosuppressive to inflammatory may provide a therapeutic advantage for transgelin-2-associated cancer treatment." (PMID 33898417, 2021).
tumor (continued). "Our group found that Tagln2 expression was significantly higher in microvascular endothelial cells (ECs) from lung cancer tumor tissues than in their paired normal counterparts, which was associated with advanced clinical stage, increased tumor size, and histological neural invasion." (PMID 34150622, 2021). "Therapeutically, targeting the TAGLN2 axis synergized with both cisplatin and bevacizumab, potently suppressing tumor progression by impairing neovascularization and promoting vascular normalization." (PMID 41824788, 2026). "In vivo, exosomal TAGLN2 accelerated tumor growth and lung metastasis by generating abnormal, leaky vasculature and hypoxia." (PMID 41824788, 2026). "While members of the transgelin family can suppress metastasis through ERK1/2 modulation and MMP-9 downregulation, TAGLN2 has shown both tumor-suppressive and oncogenic roles depending on the cancer type." (PMID 41148856, 2025). "Tumor-infiltrating CER-TAGLN2 T cells maintained high TAGLN2 expression and surface levels of FABP5 compared to control CER T cells present at the same tumor sites." (PMID 39948077, 2025). "At the same time, later research correlated the overexpression of TAGLN2 in advanced stages with tumor progression via the TGFβ signaling pathway." (PMID 41450913, 2025). "We observed aberrantly upregulated TAGLN2 expression in the early stage of GC and TAGLN2 expression levels continuously increased with tumor progression." (PMID 39168971, 2024). "In contrast to NC group, TAGLN2-overexpressing group exhibited faster tumor growth and larger tumors." (PMID 39168971, 2024). "In 85.3% of GC patients, TAGLN2 expression in tumor tissue markedly exceeded that in paired normal counterparts, and high TAGLN2 expression (score ≥ 2) observed more frequently in tumor tissues (68% vs. 8%)." (PMID 39168971, 2024). "Conversely, in HGC-27 cells overexpressing TAGLN2 and treated with multiple anti-tumor drugs, an opposite trend was observed." (PMID 39168971, 2024). "The tumor tissues predominantly exhibited negligible TAGLN2 expression at the cancer cell membrane, yet approximately 81% of adjacent normal tissues displayed positive TAGLN2 staining at the membrane." (PMID 39168971, 2024). "More TAGLN2 accumulation was observed in stromal areas (CK- region) than in tumoral areas (CK+ region) of tumor tissues." (PMID 39168971, 2024). "TAGLN2 overexpression significantly prevented the PARP cleavage in cells induced by Dox, VP16, and IFNγ, establishing that TAGLN2 enhances tumor chemoradio resistance in vitro." (PMID 39168971, 2024). "In conclusion, the present study shows that TAGLN2 plays a specific role in tumor proliferation, migration, and invasion and is involved in chemoresistance by inducing EMT-like changes." (PMID 38509504, 2024). "The presence of TAGLN2 in the cytoplasm or nucleus was significantly greater in tumor tissues than in adjacent normal tissues (P < 0.0001)." (PMID 39168971, 2024). "Through the results of tumor weight, it was found that TAGLN2-overexpressing group exhibited higher tolerance to Cisplatin treatment than NC group (33.7% vs 57.7%), and the inhibitory ability of MK2206 treatment alone was similar (19.6% vs 18.2%)." (PMID 39168971, 2024). "We previously clarified that TAGLN2 also plays an important role in promoting tumor angiogenesis by activating NRP1/VEGFR2 and downstream MAPK signaling pathways." (PMID 39168971, 2024). "TAGLN2 expression was suppressed by small-interfering or short hairpin RNAs, and its effects on tumor biology were assessed in several BTC cell lines." (PMID 38509504, 2024). "TAGLN2, an actin-binding protein highly expressed by tumor cells, plays a crucial role in determining cell morphology and transformation and has been implicated in various human malignancies." (PMID 38509504, 2024). "Representative IHC images illustrate the aberrant expression of TAGLN2 at the early stage of GC (Stage I) and a progressive increase with tumor advancement." (PMID 39168971, 2024).